LPAR2 (lysophosphatidic acid receptor 2)
Diseases named in the same sentence as LPAR2 in open-access papers (continued):
Sharing a sentence is not in itself a finding about the gene and the disease.
cancer (31 papers, 2004 to 2025). A tumor composed of atypical neoplastic, often pleomorphic cells that invade other tissues. "LPAR1 and LPAR4 were highest in cancer-associated fibroblasts, while LPAR6 was highest in endothelial cells, and LPAR2 was highest in cancer epithelial cells." (PMID 37372960, 2023). "Regarding LPAR2, its highest expression was in cancer epithelial cells followed by normal epithelial cells, and LPAR5 expression was highest in myeloid cells followed by B-cells." (PMID 37372960, 2023). "Epithelial cell (primarily cancer cells) composition was significantly enriched in high-LPAR2 and -LPAR3-expressing tumors in all three cohorts (all p < 0.001) but decreased in high-LPAR1, -LPAR5, and -LPAR6-expressing tumors (all p < 0.05)." (PMID 37372960, 2023). "We used online tools, such as KM plotter, GEPIA2.0, UACLAN and HPA, and R software to examine the critical role of LPAR2 in predicting patient outcomes of multiple cancer types in TCGA and GEO databases." (PMID 35241179, 2022). "The effects of LPAR2 on the clinical prognosis in pan-cancer were examined using the Kaplan–Meier plotter (KM plotter) as well as Gene Expression Profiling Interactive Analysis (GEPIA), UALCAN, and Human Protein Atlas (HPA) databases." (PMID 35241179, 2022). "We used KM plotter to determine the correlation between LPAR2 expression and the survival of patients with pan-cancer and those with normal tissues." (PMID 35241179, 2022). "Our findings illustrated the expression levels and prognostic value of LPAR2 in several types of cancers, especially HNSC and KIRC." (PMID 35241179, 2022). "We examined the mRNA and protein expression levels of LPAR2 in pan-cancer and the corresponding normal tissues using Oncomine, TIMER, UALCAN, and HPA databases, as well as validated by R software in TCGA and GEO databases." (PMID 35241179, 2022). "The expression of LPAR2 was significantly correlated with the outcome of multiple types of cancer, especially HNSC and KIRC." (PMID 35241179, 2022). "LPAR2 can protect cancer cells against apoptotic stress after irradiation and chemotherapy by augmenting DNA damage repair response and inhibiting the mitochondrial apoptosis cascade." (PMID 34209775, 2021). "Since then, increased LPAR2 gene or LPA2 expression has been observed in carcinoma tissues of breast, liver and uterus, and multiple cancer cell lines." (PMID 31323936, 2019). "Taken together, these results suggest that LPAR2 signaling may be the most specific among the LPARs in mediating pro-cancer pathological processes." (PMID 37372960, 2023). "In this study, we systematically investigated the expression of LPAR2 and its relationship with pan-cancer prognosis using the Oncomine, TIMER, UALCAN, GEPIA, KM plotter and HPA databases, as well as expression and survival analysis of LPAR2 in the TCGA and GEO data was validated by R software." (PMID 35241179, 2022). "Differences in data collection methods and analytical approaches may be attributed to the heterogeneity of LPAR2 expression among cancer types and databases." (PMID 35241179, 2022). "Likewise, to validate these results, survival analysis of LPAR2 in pan-cancers of the TCGA databases was performed using the survival package via R software." (PMID 35241179, 2022). "Therefore, much further experimental validation is needed to investigate the link between the expression of LPAR2 and prognosis in cancer patients with HNSC and KIRC as well as other kinds of cancers." (PMID 35241179, 2022). "As a result, we observed the same trend in the expression of LPAR2 in pan-cancers." (PMID 35241179, 2022). "LPAR2 is implicated in numerous oncogenic pathways and has been shown to transduce growth promoting signals in the LPA-rich environments characteristic of aggressive cancers." (PMID 23426604, 2013). "Among the other LPARs, LPAR2 demonstrated the most robust expression in tumors compared to normal breast tissue and was the only LPAR to be expressed primarily in cancer epithelial cells." (PMID 37372960, 2023).
cancer (continued). "The aberrant expression of LPA receptors, particularly LPAR2 and LPAR3, has been reported in several cancers, suggesting a significant role for LPA in different cancer types through distinct signaling pathways such as AKT, MAPK, and ERK." (PMID 36551233, 2022). "These genes include well annotated tumor-suppressor genes and oncogenes (e.g., TGFBR2 and MYC as well as genes that have never been previously linked to cancer in general, or to increased BC risk (including ADCY3, ATXN7, CFL1 and LPAR2)." (PMID 36991492, 2023). "Noteworthy, LPAR2 activation may exert anti-migration effects by blocking EGF-induced migration and invasion of pancreatic Panc-1 cancer cells through the G12/13/Rho signaling pathway." (PMID 34209775, 2021).
LPAR2 also shares sentences with these, for which no sentence is quoted: asthma (4 papers); hepatocellular carcinoma (4); neuroblastoma (4); prostate carcinoma (3); bladder cancer (2); diabetes (2); experimental autoimmune encephalomyelitis (2); glioblastoma (2); ischemic stroke (2); osteosarcoma (2); adenomyosis (1); adrenocortical carcinoma (1); allergic asthma (1); Alzheimer disease (1); amyotrophic lateral sclerosis (1); atherosclerosis (1); benign ovarian tumors (1); cardiac ischemia (1); cervical cancer (1); cervical squamous cell carcinoma (1); chronic ischaemic heart disease (1); chronic leukemia (1); congenital hydrocephalus (1); COVID-19 (1); depression (1); ductal carcinoma (1); endocervical adenocarcinoma (1); endotoxemia (1); eosinophilia (1); epithelial dysplasia (1).
A further 28 diseases each share a sentence with LPAR2 in 1 paper.